ACE (angiotensin I converting enzyme)
Diseases named in the same sentence as ACE in open-access papers (continued):
Sharing a sentence is not in itself a finding about the gene and the disease.
chronic kidney disease (continued). "Hyperkalemia, conversely, arises most commonly in patients with chronic kidney disease, metabolic acidosis, or those receiving potassium-sparing diuretics, angiotensin-converting enzyme (ACE) inhibitors, or angiotensin II receptor blockers (ARBs)." (PMID 41393542, 2025). "Summary of randomized controlled trials evaluating ACE inhibitors and ARBs in chronic kidney disease." (PMID 41189867, 2025). "ACE inhibitors are also beneficial for patients with HF and chronic kidney disease due to their protective effects on the heart and kidneys." (PMID 39273041, 2024). "For patients with proteinuria, starting treatment with angiotensin-converting enzyme (ACE) inhibitors early can delay the onset of end-stage renal disease." (PMID 37895203, 2023). "Angiotensin converting enzyme (ACE) inhibitors are a class of drugs that can effectively reduce the systemic vascular resistance of patients with chronic kidney disease, thereby achieving long-term renal protection." (PMID 38179301, 2023). "Our results are generalisable only to regimens that include the use of ACE inhibitors or ARBs as first-line agents (as is usually the case in children with chronic kidney disease)." (PMID 36442482, 2023). "The results also showed an even higher reduction in AKI patients with mild chronic renal insufficiency who were also treated with an angiotensin-converting enzyme inhibitor (ACE inhibitor)." (PMID 35873578, 2022). "Current management of FLD is preventative and involves lipid lowering therapy, ACE inhibitors, diuretics and steroids, in order to delay progression to end-stage renal disease: for many in Latin America, these medications will be an out of pocket expense." (PMID 34256778, 2021). "Indeed, increased levels of ACE and Ang-II have been implicated in the pathophysiology of lung (pulmonary hypertension, pulmonary fibrosis, acute lung injury and acute respiratory distress syndrome) and kidney disease (chronic kidney disease, diabetic nephropathy)." (PMID 32901433, 2021). "The mainstay of therapy for chronic kidney disease is control of blood pressure and proteinuria through the use of angiotensin-converting enzyme inhibitors (ACE-Is) or angiotensin receptor blockers (ARBs) that were introduced more than 20 years ago." (PMID 33477669, 2021). "Patients with blood hypertension had ACE-inhibitors applied to prevent progression to an end-stage renal disease." (PMID 32414085, 2020). "Once microalbuminuria developed, treatment with ACE-inhibitors was introduced to prevent progression to end-stage renal disease." (PMID 32414085, 2020). "The patient received ACE inhibitors, with a remission of the nephrotic syndrome, but with a progressive deterioration of renal function leading to end-stage renal disease 10 years later." (PMID 32646497, 2020). "Percentage of Mo2 increased in many inflammatory diseases including chronic kidney disease (CDKs), which expresses higher level of ACE along with CD14 and CD16." (PMID 32508938, 2020). "In inflammatory diseases, including granuloma, atherosclerosis, chronic kidney disease and bacterial infection, ACE expression gets upregulated in immune cells, especially in myeloid cells." (PMID 32508938, 2020). "In children with ADPKD who have proteinuria, ACE inhibitors or ARBs should be used as the primary treatment as in other chronic kidney diseases." (PMID 31118499, 2019). "In each analysis (T2DN vs T2DM; end-stage renal disease [ESRD] vs normal), the presence of the ACE insertion was associated with a lower risk of developing the CKD phenotype in the respective populations." (PMID 31048445, 2019). "ACE inhibitors serve to increase levels of bradykinin and are routinely used to treat chronic kidney diseases." (PMID 30405320, 2018).
chronic kidney disease (continued). "If ERT is started, angiotensin-converting enzyme (ACE) inhibitors or angiotensin II receptor blockers (ARB) should be started or continued according to the treatment guidelines for chronic kidney disease (KDIGO) and cardiovascular disease (ESC)." (PMID 25885911, 2015). "To further address this question we tested the role of monocytic-ACE in promotion of atherosclerotic events in vitro under conditions mimicking those of chronic renal failure." (PMID 25003524, 2014). "In controlled trials in Chronic Kidney Disease, Angiotensin Converting Enzyme (ACE) inhibitors and Angiotensin Receptor Blockers (ARB) reduce protein excretion by approximately 35% to 40%." (PMID 24955116, 2014). "A benefit of dual RAS inhibition, of telmisartan and ACE inhibitors was apparent in a small study (n = 332) in patients with end-stage renal disease (ESRD) in addition to HF and impaired left ventricular ejection fraction (LVEF)." (PMID 23866091, 2013). "In another small study of ten children with chronic kidney disease and proteinuria that employed a cross-over design, combination therapy with an ACE inhibitor and an ARB reduced proteinuria to a significantly greater extent than either agent alone." (PMID 22461141, 2013). "Although ACE inhibitors are successful in delaying the progression of chronic renal failure, few alternative treatment options exist and thus there is great medical need for novel strategies combating this disease." (PMID 24244677, 2013). "First, ACE inhibitor therapy at doses that achieve suppression of proteinuria has been used with a high degree of safety in children with chronic kidney disease." (PMID 22461141, 2013). "Current clinical strategies in slowing the progression of chronic kidney disease mainly involve ACE inhibitors and AT1 receptor blockers." (PMID 24244677, 2013). "In experimental models of chronic renal disease and in human diabetic nephropathy, pharmacological blockade of ACE significantly slows down the rate of decline in renal function." (PMID 17042963, 2006). "Effect modification with benefit for DD carriers and treatment failure for II carriers was also present for diastolic blood pressure, decline of glomerular filtration rate, ACE activity and progression to end-stage renal disease." (PMID 16242049, 2005). "It is tempting to speculate that in early CKD stages, ACE expression may be still regulated by the renin-angiotensin-aldosterone system, whereas this regulatory loop is abrogated in end-stage renal disease." (PMID 39717170, 2024). "Fish residual proteins contain motifs with angiotensin-I converting enzyme (ACE) inhibitor properties, which is of interest as treatment with ACE inhibitor drugs are used to delay the progression of chronic kidney disease and amend proteinuria in patients with kidney disease." (PMID 37550593, 2023). "In addition, 2 patients have stage III and stage IV chronic kidney disease and 12 patients have albuminuria and/or treatment with ACE inhibitors." (PMID 34608521, 2022). "In this study, we aimed to analyze the association between ACE I/D polymorphism and cardiovascular mortality risk among non-hemodialyzed chronic kidney disease patients." (PMID 35885904, 2022). "Other studies have shown that long-term exposure of patients with compensated liver cirrhosis (Child-Pugh class A) to ACE inhibitors does not increase the risk of end-stage renal disease." (PMID 35801591, 2022). "Chronic kidney disease (CKD) patients, especially diabetic patients with SARS-CoV-2, are at a higher risk of AKI due to baseline upregulation of angiotensin-converting enzyme (ACE) and downregulation of ACE-2 protein." (PMID 35960124, 2022). "Inhibitors of the renin‐angiotensin system (RAS), particularly angiotensin (Ang) II receptor blockers (ARBs) and angiotensin‐converting enzyme (ACE) inhibitors, are widely adopted antiproteinuric and antihypertensive agents that prevent the progression of chronic kidney disease." (PMID 34042270, 2021).
chronic kidney disease (continued). "ACE inhibition and hydroxyurea decrease proteinuria so they may limit progression of chronic kidney disease." (PMID 30305036, 2018). "Additionally, it was proved, that in patients with chronic kidney disease a combination of ACE inhibitor and sartans allows to achieve even greater reduction of arterial stiffness than the treatment with only one of mentioned drugs." (PMID 28114900, 2017). "Based on crucial roles of RAS in the pathogenic development of chronic kidney disease (CKD), we tested the hypothesis whether plasma ACE and ACE2 levels might be significantly changed in the patients with end-stage CKD (ESRK), i.e., uremic patients." (PMID 29157100, 2017). "Angiotensin converting enzyme inhibitors (ACE inhibitors) are a well-established treatment to reduce proteinuria of glomerular origin and to slow down the decline of glomerular filtration rate in chronic renal failure." (PMID 27102039, 2016). "Moreover, ACE inhibitors attenuate the inflammatory response during chronic renal failure by preventing local AngII production." (PMID 24244677, 2013). "Ten children with chronic kidney disease and persistent proteinuria, despite maximal doses of an ACE inhibitor, exhibited a sustained reduction in proteinuria after addition of losartan, with no significant changes in blood pressure or glomerular filtration rate." (PMID 22461141, 2013). "Moreover, 66.2% chose ACE inhibitors as the first-line drugs for patients with chronic kidney disease and proteinuria." (PMID 18425285, 2008). "Community advice should include warnings for people with chronic kidney disease (CKD), heart failure, or those taking ACE inhibitors." (PMID 41585888, 2025). "ACE inhibitor therapy can often improve renal blood flow (RBF) and sodium excretion rates in congestive heart failure (CHF) and slow down the progression of chronic renal disease, but it can also cause a syndrome of “functional renal insufficiency” and/or hyperkalemia." (PMID 40137155, 2025). "In the therapeutic management of chronic kidney disease (CKD), it is now well known that medication with angiotensin I-converting enzyme inhibitors or angiotensin II (Ang II) receptor blockers is strategically essential." (PMID 37333473, 2023). "Previous evidence suggested that such an adverse event often occurs when ACE inhibitors are concomitantly prescribed with potentially interacting drugs, such as spironolactone or chlorothiazide, or when patients have certain comorbidities, such as chronic kidney disease." (PMID 35886227, 2022). "This is because 170 (60.4%) patients did not meet the diagnosis of chronic kidney disease, indicating that the patients could tolerate the renal ischemia caused by ACE inhibitors and ARBs." (PMID 35909129, 2022). "ACE inhibitors are considered first line of treatment in patients with many forms of chronic kidney disease (CKD)." (PMID 28542215, 2017). "Angiotensin-converting enzyme (ACE) inhibitors (ACEIs) are used in the management of various diseases in cats, notably chronic kidney disease (CKD)." (PMID 27338786, 2016). "More importantly, spironolactone has been reported to further decrease proteinuria in patients with chronic kidney disease already on chronic treatment with ACE inhibitors suggesting that aldosterone antagonists may also add to the renoprotective effect of RAAS inhibition in humans." (PMID 27713239, 2010). "In our model of chronic renal failure, the expression of the acute injury marker, kidney injury molecule (KIM)-1, was similar in kidneys from the vehicle-treated wildtype and ACE−/− mice." (PMID 36520238, 2023). "Another study investigated the effect of long-term ACE inhibition on cardiac and renal ACE2 in rats in chronic kidney disease induced by subtotal nephrectomy." (PMID 33762942, 2021).
chronic kidney disease (continued). "Enalapril is an ACE inhibitor used for the treatment of hypertension, heart failure, and chronic kidney diseases (CKD) and, although it is a commonly prescribed drug, the effect of enalapril therapy shows significant interindividual variability that is not completely understood." (PMID 33007874, 2020). "Clinical trial evidence indicates that the blockade of the RAS by ACE inhibitors or AT1 receptor blockers (ARB) has been shown to alleviate renal injury, improve renal function and reduce renal events in patients with chronic kidney diseases and ESRD." (PMID 26245758, 2015). "Chronic kidney disease (CKD) blunts erythropoietin production, a proanemic effect that is compounded by other factors such as accelerated erythrocyte destruction and widespread use of concomitant medication such as ACE inhibitors and ARBs." (PMID 24883202, 2014). "Toxic substances in the blood of patients with uremia due to End Stage Renal Disease (ESRD) can induce local conformational changes in the ACE protein globule and alter the efficacy of ACE inhibitors." (PMID 23166630, 2012). "The term “chronic kidney disease” (CKD) gained widespread adoption in medical practice during the 1990s, coinciding with clinical trials that demonstrated angiotensin-converting enzyme (ACE) inhibitors could significantly slow the progression of kidney damage, irrespective of the cause." (PMID 40004772, 2025). "The search strategy used a combination of Medical Subject Headings (MeSH) and free-text terms, including "chronic kidney disease", "CKD", "proteinuria", "albuminuria", "ACE inhibitor", "angiotensin receptor blocker", "ARB", "RAAS blockade", and "randomized controlled trial"." (PMID 41189867, 2025). "Even among patients without chronic kidney disease, 45% were not on ACE inhibitors/angiotensin II receptor blockers." (PMID 35641098, 2022). "In addition, in a prospective clinical trial of 151 patients with chronic renal failure (CRF), the frequency of end-stage renal failure in the RRR group was 52% lower than that in the ACE inhibitor group." (PMID 35924053, 2022). "A prospective study on 108 smokers with non-diabetic chronic kidney disease treated with ACE inhibitor therapy showed that smoking attenuated the renal protection achieved by ACE inhibition." (PMID 36589440, 2022). "For example, it was noticed that most of the HCPs prefer not to prescribe an ACE inhibitor for a patient with any degree of chronic kidney disease." (PMID 32695426, 2020). "In humans it has been reported in a study performed on eight patients with chronic kidney disease and persistent proteinuria treated with spironolactone, an antagonist of the AT1-R, in addition to ACE inhibitors therapy, a drastic reduction in proteinuria levels (54%) after four weeks of treatment." (PMID 27347925, 2016). "Consequently, ACE inhibitors (e.g., Captopril) and angiotensin II type 1 (AT1) receptor blockers (ARBs) (e.g., Losartan) represent, nowadays, important therapeutic strategies against CVD, chronic kidney disease, and type 2 diabetes." (PMID 38543635, 2024). "Neither an ACE inhibitor nor an angiotensin receptor blocker is recommended for the primary prevention of chronic kidney disease in diabetics with normal blood pressure, urine albumin-to-creatinine ratio (< 30 mg/g creatinine), and normal estimated glomerular filtration rate." (PMID 38012781, 2023). "Loop diuretics, ACE inhibitors/AT1 blockers or pre-existing chronic kidney disease had no impact." (PMID 37452960, 2023). "The inhibition of RAS with ACE inhibitors (ACEi) and AngII receptor blockers (ARB) is a cornerstone in the management of patients with chronic kidney disease (CKD), presenting additional kidney protection beyond their blood pressure (BP)-lowering effect." (PMID 36139118, 2022). "Therefore, ACE inhibitors (ACEi) and AT1 receptor blockers (ARBs) have been used as first-line therapies to reduce the progression of chronic kidney diseases (CKD)." (PMID 23762470, 2013).
chronic kidney disease (continued). "In the ACE inhibitor (ACEI)/angiotensin receptor blocker (ARB) and pre-end-stage renal disease (pre-ESRD) program cohort, 207 MgO users and 1,401 non-users were included; after matching, 151 MgO users and 302 non-users remained." (PMID 41938509, 2026). "ACE inhibitors or ARBs are the preferred first-line therapy for managing blood pressure in patients with diabetes, hypertension, an eGFR <60 mL/min/1.73 m2, and a UAC ≥ 30 mg/mmol, due to their established benefits in preventing the progression of chronic kidney disease (CKD)." (PMID 40575571, 2025). "The development of ACE inhibitors (ACEi), and later of AT1R blockers (ARBs), revolutionized the therapeutic approach to kidney and heart diseases, where both groups of RAAS blockers attenuate cardiac and renal remodeling and slow down the progression of HF and chronic kidney disease (CKD)." (PMID 36237903, 2022). "Sequential blockade of the RAAS with ACE inhibitor and ARB has been shown to be effective in reducing proteinuria and preserving renal function in patients with non-diabetic chronic kidney disease." (PMID 27713239, 2010). "ACE inhibitors and ARB have been shown to have a renoprotective effect and reduced morbidity and mortality in patients with chronic kidney disease However, the strategy of dual RAAS inhibition seems to have different clinical impacts in diabetic and non-diabetic CKD patients." (PMID 22917002, 2012).